CD44 (CD44 molecule (IN blood group))
Diseases named in the same sentence as CD44 in open-access papers (continued):
Sharing a sentence is not in itself a finding about the gene and the disease.
tumor (continued). "CD44 is expressed in CSC, as well as in a variety of normal stem cells, and plays an important role in CSC self-renewal and proliferation, leading to tumor growth, tumor metastasis, the activation of stemness transcription factors such as Nanog, Sox2, and Oct4, and chemotherapy resistance." (PMID 35456011, 2022). "As expected, A higher expression level of CD44 protein was found on B16‐F10 cells than that on PIG1 and HL‐7702 cells, which guarantees the excellent HA‐mediated tumor targeting capability of HZ." (PMID 34913610, 2022). "For the interaction between HA and CD44 and a large amount of oxygen dissolved in the PFC core, O2@PFC@FHA NPs not only improved the tumor targeting but also enabled more oxygen to reach the hypoxic area of the tumor." (PMID 36873299, 2022). "A recent study has revealed that CD44 exists as homodimers in tumor cells rather than in normal cells." (PMID 35733341, 2022). "Tumor-incidence declined from 100% to 60% in the 104-cell group, 100% to 40% in the 5000-cell group, and 80% to 40% in the 2500-cell group with PFK158-pretreated ALDH+CD44+ SKOV3 cells." (PMID 35155224, 2022). "Thus, the median transcript levels of hyaluronic acid synthase 1 (HAS1) and major HA receptors CD44 and RHAMM were elevated 3 to 25-fold in those tumor tissues when compared with normal tissues." (PMID 35528727, 2022). "Moreover, increased CD44 immunoexpression was more common in patients with AJCC stage III and T3 tumours." (PMID 35296132, 2022). "We could also show co-localization of CD44 and HGF in the parental tumor tissues, validating the relevance of predicted interactions from our co-culture model in the in vivo context." (PMID 36273171, 2022). "The expression of tumor stem cell markers (CD44, CD133, and OCT4) were also notably increased by exosomal miR-4800-3p and miR-4800-3p mimic, respectively, while knockdown of miR-4800-3p decreased these tumor stem cell markers." (PMID 35756606, 2022). "Finally, when CD44+CD133+ tumor-initiating Caco-2 cells were injected into NSG mice, Juglone or KPT6566 led to a meaningful reduction in tumor volume and mass compared with tumors isolated from mice that received control treatment." (PMID 35433695, 2022). "Moreover, the expression of CD44 and SOX9 increased according to tumor grade in the samples of patients." (PMID 35205666, 2022). "The combination therapy also enhanced the high infiltration of effector CD44+ and CD69+ CD8+ PD-1− on both sides of tumor, which may have a role in the antitumor response." (PMID 36513720, 2022). "The number of CSCs with the EpCAM+CD44+MET+CD47+ phenotype increased with tumour progression, while no significant changes were found in the number of CSCs representing the main population of tumour cells." (PMID 35563449, 2022). "Using unsupervised hierarchical clustering of six subtyping genes assessed by multiplex RNA hybridization (basal differentiation: KRT5, KRT14, CD44; luminal differentiation: KRT20, GATA3, and FOXA1), 28 tumor samples were each classified as either basal or luminal subtypes." (PMID 36142180, 2022). "In GBM with high CD44 expression, EMP3 is frequently up-regulated and might be a vital role in tumor initiation and advancement in primary GBM." (PMID 36217151, 2022). "As a primary component in ECM, HA or LMW-HA can be recognized by various types of cells including cancer cells through HA receptors (such as CD44, RHAMM, etc), thereby playing pivotal roles in many biological processes such as tumor invasion, proliferation, and inflammation." (PMID 36419650, 2022). "Additionally, TCF64-ORF-T expressed higher levels of the stemness markers, CD44 and ALDH1, but lower level of CD24 as compared to the control tumor TCF64-Ctl-T." (PMID 36359766, 2022). "Furthermore, tumor growth was observed in all subpopulations except CD105- and CD44+/CD105+ subpopulations." (PMID 36612281, 2022).
tumor (continued). "Finally, to investigate the effects of Juglone or KPT6566 treatment on tumor-initiating cell-induced tumorigenesis, the in vivo anti-tumorigenic properties of Juglone and KPT6566 were examined in NSG mice bearing CD44+CD133+ Caco-2 cell xenografts." (PMID 35433695, 2022). "Images of immunohistochemically stained tissue samples showed that CD44 was almost not expressed in normal tissues with a quantity of < 25% but that it was significantly overexpressed in tumour tissues with a quantity of 75%–25%." (PMID 36316684, 2022). "Further analyses revealed that the activation of the FOXM1 (oncoprotein) transcription factor is a key factor in cell dedifferentiation, which enables tumor cells to acquire an epithelial-mesenchymal transition phenotype and increases the LCSC surface marker CD44." (PMID 36613925, 2022). "Interestingly, there was a positive correlation between CD44+ and CD69+ expression on CD8+ PD-1− TILs on both sides of tumor." (PMID 36513720, 2022). "Therefore, while CD44 and CDK12 likely represent only one of several cellular targets for each sdRNA, this study has redefined the CD44 and CDK12 tumor suppressive axes to include sdRNAs as potent regulators." (PMID 35455981, 2022). "Moreover, outside of the tumor, splenic CD8 T cells from lean and obese mice secreted similar levels of IFN-γ, TNF, and GzmB and expressed similar levels of CD69, CD44, CD36, Eomes, and T-bet." (PMID 35103755, 2022). "Combining with the upshifted association of CD44 and FERM in the nonraft, a stimulator of tumor cell migration, it is surmised that CD44s modified by palmitoylation exist as monomers when approaching the lipid raft." (PMID 35733341, 2022). "CD44 is a cell surface receptor for its main ligand hyaluronic acid (HA) which stimulates various oncogenic signaling pathways (e.g. Rho GTPases, PI3K/AKT, and MAPK signaling pathways) resulting in tumor cell survival, proliferation, migration and invasion." (PMID 36505828, 2022). "In accordance with the literature, we showed that SCLC cells which metastasize into the lymph nodes, but not the primary tumor tissues, were highly positive for CD44." (PMID 34228218, 2022). "We found that the extent of tumour burden from co-injected populations in the presence of HA-CPNs was significantly decreased for CD44 + derived foci but not for CD44- ones at 24hpi and 4dpi of the time course (right)." (PMID 35840697, 2022). "The use of GK921, an inhibitor that specifically blocks TG2’s catalytic activity, reduced CD44 and master transcription factor expression levels which in turn blocked cell growth in MES subtype cells and tumor formation in an GBM orthotopic xenograft mouse model." (PMID 35681474, 2022). "Furthermore, the downregulation of MK expression with quercetin binding limits CD44+/CD133+ migration and the development progression of tumor cells as well as PCa cells." (PMID 35684449, 2022). "Silencing each of CD44 and FN1 reduced MSN's anti-tumor effect and their effects were additive." (PMID 34976221, 2022). "Further investigation of the regulatory mechanism may provide better insight into the precise roles of Hsp90ab1, MSN, CD44, and FN1 in the anti-tumor action of Lrp5 CM." (PMID 34976221, 2022). "HA fragments during interaction with CD44 might enroll ERM proteins, which can interact with VEGFR, contributing to angiogenesis by promoting vessel formation and tumor cell migration." (PMID 36613567, 2022). "Since CD44 is known to bind VCAM-1, which decreases tumor growth, it is possible that Quercetin could reduce the expression of VCAM-1 and therefore endothelial activation." (PMID 35336985, 2022). "A cluster of differentiation 44 (CD44), a transmembrane molecule, senses microenvironmental tumor changes by linking to ECM constituents, such as hyaluronic acid (HA), and promotes extracellular signals to control tumor development." (PMID 36289931, 2022).
tumor (continued). "Moreover, subsequent WB and qRT-PCR test provided intriguing evidences that OTUB1 overexpression also considerably enhanced stem-cell markers of CRC tumor including CD133 and CD44." (PMID 35354355, 2022). "In addition, our clinical analysis and the results from xenograft metastatic mouse model further support these findings by unveiling a positive correlation between the expression of CD44 and AKT phosphorylation in the OSCC tumor tissues." (PMID 35629265, 2022). "Several biomarkers, including aldehyde dehydrogenase (ALDH), cluster of differentiation 44 (CD44), and octamer-binding transcription factor (OCT4), have been used to identify tumor stem cells in various tumors, including, tongue squamous cell carcinoma and major and minor salivary gland neoplasms." (PMID 35626430, 2022). "CD44, an upregulated FRG in SCC, is highly correlated with immune function in this study, and plays an important role in biological processes such as inflammation response, extracellular matrix remodeling, and tumor cell invasion and metastasis, and EMT." (PMID 35501667, 2022). "For instance, H-Ras, CD44, PXN-AS1, macroH2A1, etc., are important tumor-related factors; therefore, the dysregulation of DDX5/DDX17 action is closely related to tumorigenesis and tumor progression." (PMID 35992805, 2022). "CPPA treatment significantly inhibits invasion, migration, and adhesion in tumor cells by down regulating the CD44 expression, indicating that CPPA may be a potential candidate for the prevention of tumor metastasis." (PMID 35464007, 2022). "We show here that CD44 (a transmembrane marker of CSC and EMT phenotypes) contributes to regulate TF expression at a transcriptional level, thereby supporting procoagulant properties in tumor cells that facilitate their metastatic spread." (PMID 35805061, 2022). "CD44 is a non-kinase glycoprotein located in the transmembrane space and is highly expressed in tumor stem cells." (PMID 36313570, 2022). "Interestingly, tumor cells in cancer nests showed low to moderate levels of PKD1 expression, along with low levels of CD44 expression." (PMID 36497140, 2022). "Lack of CD44 appears to completely hinder the ability of primary microglia to upregulate MMP9 in response to tumor cells." (PMID 35992852, 2022). "Total CD44 expression was higher in tumor tissue, compared with paired non-invaded peritumor samples in 78.95% of cases, whilst in the remaining 21.05% the difference between paired samples was biologically insignificant." (PMID 36291969, 2022). "Juglone meaningfully suppressed the growth of both CD44+CD133+ tumor-initiating Caco-2 cells and ΔCD44+CD133+ non-tumor-initiating Caco-2 cells in a concentration-dependent manner." (PMID 35433695, 2022). "Cells expressing CSC markers (e.g., CD44+/CD24−) and with high aldehyde dehydrogenase (ALDH) activity were identified as a subset of cells in both breast cancer cell lines and human tumor tissues that could self-renew and initiate and maintain tumor growth." (PMID 35406489, 2022). "The CD44 + CD24 + ESA+ phenotype has a 100-fold higher tumor-initiating capacity than non-tumorigenic cancer cells, and these cells display distinctive stem cell features, including self-renewal and the ability to generate phenotypically diverse progeny." (PMID 36605595, 2022). "CD44-cancer cells (C4, C5), CSCs (C7, C9, and C12) and other CD44+ cancer cells (C0, C1, C2, C3, C6, C8, C10, and C11) presented different signaling communication patterns in TME, demonstrating intra-tumor heterogeneity." (PMID 36451812, 2022). "It has been established previously that upon sequential proteolytic cleavage CD44 can produce CD44 intracytoplasmic domain (ICD) tail which translocates to the nucleus, and is involved in transcription of genes responsible for tumor invasion and therapy resistance." (PMID 35840697, 2022).
tumor (continued). "The CNVkit SCNA analysis also highlights the potential importance of oncogenes (e. g., RCP, CD44, WT1, BCL2L2, and AKT2) and tumor suppressors (e. g., PRKCDBP) to TNBC etiology and metastatic progression, as significant amplicons/deleted regions harbor these genes." (PMID 35992833, 2022). "Current research revealed that epidermal growth factor receptor (EGFR) reinforced CD44-mediated TNBC cell clustering, whether blockade of EGFR has synergistic effects on erastin-induced tumor inhibition of CSC clusters is still poorly understood." (PMID 35725558, 2022). "Silencing CD44 and FN1 in EO771 cells and MDA-MB-231 cells downregulated MTT-based viability as well as the expression of Lrp5, MMP9, Runx2, and Snail in EO771 cells, whereas their silencing significantly suppressed MSN-induced tumor inhibition." (PMID 34976221, 2022). "Cell—cell communication analysis revealed that SPP1/CD44 interactions between SPP1+ macrophages and their localized tumor epithelial cells could activate downstream target genes in epithelial cells to promote dynamic changes in intratumor heterogeneity." (PMID 36612160, 2022). "Protein–protein interaction of the gene in the ceRNA networks shown that the high-scoring proteins were obtained including CD44, MYC, CCND1, ESR1, IL6, and VEGFA, which suggesting that they might jointly regulate the occurrence and development of tumor." (PMID 34655361, 2021). "The CD44+EGFR+ double-positive tumor cells (Q2) showed highest cluster formation ability compared to the CD44+EGFR- single-positive cells (Q4) or CD44-EGFR- double-negative cells (Q3)." (PMID 33995681, 2021). "The CXCR4 expression on tumor cells is upregulated by hypoxia and by other angiogenic factors, which are capable of directing the trafficking of normal and malignant cells expressed high levels of CXCL12 and CD44 43-45." (PMID 34093792, 2021). "Furthermore, histological analyses of primary tumours obtained from CRC xenograft mice revealed that miltefosine treatment reduced the expression of both CHEK1 and CD44." (PMID 34841679, 2021). "Furthermore, PRDX2 depletion markedly suppressed CD133+CD44+ CCSC stemness maintenance, tumor initiation, migration and invasion and liver metastasis." (PMID 33819194, 2021). "Similarly, CD44+/CD24− CSCs were present at low frequency in TUBO tumours and slightly increased in BALB-neuT tumours, while they were abundant in both 4T1 and TS/A tumours, in agreement with the results obtained in vitro." (PMID 33257841, 2021). "On the other hand, moderate and strong staining patterns for CD44, DPP4, and SLC7A11 were observed in the cytoplasm and cell membrane of tumor tissues, while NCOA4 only exhibited weak positive staining on the cell membrane of tumor tissues." (PMID 34370716, 2021). "In conclusion, CO-HPPH-TH302/Lipo can specifically target cancer cells highly expressing CD44, increase the drug concentration in tumor tissues and reduce drug aggregation in nontarget tissues." (PMID 34011362, 2021). "Interestingly, although BCSC4 showed a higher percentage of CD44+/CD24− cells compared to BCSC3, it showed lower colony formation capacity in vitro and slower tumor growth in vivo." (PMID 33670400, 2021). "Furthermore, the Sali-loaded nanoparticles decreased the expression of CD44 and CD133, and reduced the tumor seeding ability and tumor growth rate in tumor-bearing mice, compared to the free drug, suggesting the cervical CSC targeting ability of Sali." (PMID 34452081, 2021). "The ability of BCSCs to promote tumor formation is characterized by a high expression of surface marker CD44 and a low or complete absence of surface marker CD24 (CD44+/CD24−/low)." (PMID 33925129, 2021). "This nanoplatelet could target the tumor site under the guide of CD44 on the platelet membrane, and due to the presence of CNs and PFP, it could ablate tumor cells upon laser irradiation, which promoted the release of DOX at the tumor site." (PMID 34834304, 2021).
tumor (continued). "They proposed that ALDH1A1 high/CD44 low/EGFR low tumor cells may be stationary and quiescent, while ALDH1A1−/CD44 high/EGFR high cells may be invasive and migratory." (PMID 34359786, 2021). "While normal colonic mucosa does not express CD44 isoforms, its tumours present an extensive variation of CD44 isoforms." (PMID 34944493, 2021). "We further showed that PRDX2 is functionally required for CD133+CD44+ CCSC stemness maintenance, tumor initiation, migration and invasion, and liver metastasis, and the expression of various EMT markers and Wnt/β-catenin signaling proteins was altered after PRDX2 inhibition." (PMID 33819194, 2021). "The adhesion receptor CD44 was also downregulated by the curcumin plus light combination but not when the tumor cells were exposed to curcumin or light alone." (PMID 34576132, 2021). "We observed a 1.9-fold depletion in the proportion of the CD44+CD24−/low TIC population in combination-treated tumours, but not in those treated with either inhibitor alone." (PMID 33772015, 2021). "In addition, BCSCs expressing both CD24- CD44+ and ALDH+ are recognized as highly purified BCSCs, exhibiting the greatest tumor-initiating capacity." (PMID 34801088, 2021). "Our findings support the notion that TRAF4/6 mediates pro-tumorigenic effects of CD44, and suggests that inhibitors of CD44 signaling via TRAF4/6 and RAC1 may be beneficial in the treatment of tumor patients." (PMID 33804427, 2021). "Both OB-RES and DIO therapy-treated mice displayed a significant increase in CD44+CD4+ TILs at day 27–28 compared to no therapy controls, likely due to tumor-induced reductions in the CD44+CD4+ TIL population that occurred in the absence of therapy." (PMID 34064933, 2021). "Otherwise, tumor cells in hypoxia could inhibit TAMs activation via HLA-G/LILRB interactions, assist TAMs polarization via CD44-related communication, and inhibit T-cell activation via PDCD1 and TIGIT." (PMID 34956900, 2021). "In addition, the miR-126 inhibitor obviously decreased the ratio of CD44+ CD90+ CD133+ cells, as well as the levels of IL-1α, SRY, Oct4, IL-6, and TGF-β in tumor tissues of mice." (PMID 34746322, 2021). "Notably, high levels of CD44, CD133, Nestin and MYC protein were detectable in adherently grown CSC populations from all tumor types as well as in spheres derived from ECSC_b and GSC_c." (PMID 33800955, 2021). "A nanoplatform of hyaluronic acid, which modified CD44+ tumor-targeting ligand and loaded with foreign antigen ovalbumin (OVA), realized preferential aggregation on tumor surface, phagocytosis by tumor cells, degradation by hyaluromycin, and release of OVA intracellularly." (PMID 34575414, 2021). "Cleavage of CD44 has been observed in several types of tumors, and increases in response to stimulation with fragmented hyaluronan, activation of protein kinase C (PKC), and activation of RAS, and CD44 ICD has been shown to promote epithelial–mesenchymal transition and the stemness of tumor cells." (PMID 33804427, 2021). "Interestingly, the co‐localized fluorescence signals of CD44 and EVs were only detected in PHA‐EV‐treated tumour tissue." (PMID 33738083, 2021). "Finally, the K-RAS/ERK/CD44 axis promotes infiltration and mesenchymal shift of GBM cells through SRC activation, resulting in tumor aggressiveness." (PMID 34681583, 2021). "We observed novel tumor-initiating cell-like characteristics in a CD44+CD133+ subpopulation of Caco-2 cells, and showed that treating this subpopulation with XAV939 repressed tumor-initiating properties, including suppression of cell proliferation in culture and tumorigenic potential in mice." (PMID 33994850, 2021).